ASGR1 (asialoglycoprotein receptor 1)
Diseases named in the same sentence as ASGR1 in open-access papers (continued):
Sharing a sentence is not in itself a finding about the gene and the disease.
atherosclerosis (continued). "Since several studies have demonstrated that PON2 has a positive effect on atherosclerosis, we aimed to investigate the effect of PON2 on endogenous ASGR1 expression and further explore the follow-up effects of this impact." (PMID 39055948, 2024). "To this aim, we have generated double-knockout mice lacking ASGR1 (ASGR1−/−) and ApoE−/− and characterized the development of atherosclerosis." (PMID 39616371, 2024). "By Sudan IV Staining of the aorta, neither ASGR1-/- pigs nor WT controls showed atherosclerotic lesions, suggesting that pigs do not easily develop atherosclerosis on a standard diet." (PMID 34762653, 2021). "Deficiencies of ASGR1 significantly reduce plasma non-HDL-C and TG levels, and ASGR1+/- pigs were strongly protected against HFHC diet-induced atherosclerosis." (PMID 34762653, 2021). "The other functions of ASGR1 that are not related to LDLc regulation but affect inflammation, atherosclerosis, and cardiovascular health are yet to be identified." (PMID 34508778, 2021). "Similarly, ASGR1-deficient pigs fed a high-fat diet exhibit reduced non-HDL-C levels and attenuated atherosclerosis, with underlying mechanisms involving downregulation of cholesterol synthesis and enhanced clearance." (PMID 40852369, 2025). "In conclusion, our results showed that inhibition of ASGR1 in pigs may be a safe and effective way for lipid reduction, and the role of ASGR1 in the APMK-autophagy pathway is worth exploring, which may uncover the additional protective effect against atherosclerosis of ASGR1." (PMID 39055948, 2024). "For example, ASGR1-deficient pigs show lower levels of non-HDL cholesterol and less atherosclerotic lesions than that of controls, therefore targeting ASGR1 might be an effective strategy to reduce hypercholesterolemia and atherosclerosis." (PMID 36782330, 2023).
Hypercholesterolemia (8 papers, 2021 to 2026). An increased concentration of cholesterol in the blood. "To investigate the role of ASGR1 deficiency on plasma lipid profile during hypercholesterolemia, we fed ApoE−/− and ApoE−/−/ ASGR1−/− mice with western-type diet (WTD) for 16 weeks." (PMID 39616371, 2024). "ASGR1 is associated with low-density lipoprotein–cholesterol and is a target for treatment of familial hypercholesterolemia." (PMID 37940228, 2023). "Both datasets pinpoint HMGCR, one of the clinical targets for hypercholesterolemia, as a critical regulator of this protection in ASGR1 deficiency." (PMID 34762653, 2021). "In summary, genetic or pharmacological inhibition of ASGR1 exerts dual biological functions to halt hypercholesterolemia by inhibiting cholesterol synthesis while promoting cholesterol efflux and excretion from the body." (PMID 36690631, 2023). "ASGR1 holds promise as a therapeutic target for the clinical management of hypercholesterolemia." (PMID 39055948, 2024). "Analysis of Open Targets and other databases indicated evidence of drug development, including phase II-IV trials, for 6 proteins (PGF, ASGR1, F2R, TFPI, tenascin, and MMP3), with 3 related to CVD outcomes or traits (F2R for MI, TFPI for ICH, and ASGR1 for familial hypercholesterolemia)." (PMID 37940228, 2023). "In the future, the detailed mechanistic understanding of PON2’s effects on ASGR1, coupled with the in vivo evidence of its therapeutic potential, may open up new possibilities for the development of targeted therapies for metabolic diseases, particularly hypercholesterolemia." (PMID 39055948, 2024).
viral infection (7 papers, 2018 to 2025). "Particularly in hepatocytes, high ASGR1 expression markedly enhances SARS-CoV-2 binding and infection, suggesting ASGR1-mediated pathways contribute significantly to viral infection and pathogenic mechanisms." (PMID 40852369, 2025). "Beyond viral infections, the therapeutic potential of ASGR1 in cancer treatment is also gradually emerging." (PMID 40852369, 2025). "ASGR1 has emerged as a critical therapeutic target due to its involvement in a wide range of diseases, including metabolic disorders, viral infections, and cancer." (PMID 40429734, 2025). "Other roles of ASGR1 such as hepatitis C virus binding allowing viral infection or metastasis promotion by interaction with lectins in the tumor microenvironment through the EGFR-ERK pathway are also described in relation with HCC induction." (PMID 36518850, 2022). "Given that multiple viruses can exploit ASGR1 to mediate cellular entry, future research may explore the development of broad-spectrum ASGR1 inhibitors to block diverse viral infection pathways." (PMID 40852369, 2025). "In addition to its role in protein removal, ASGR1 also participates in various functions including cholesterol regulation, response to viral infections, and platelet regeneration." (PMID 40429734, 2025). "However, recent studies have revealed that ASGR1 functions extend far beyond traditional understanding, emerging as a critical molecule linking immune regulation, viral infection, tumor progression, lipid metabolism, and targeted drug delivery." (PMID 40852369, 2025). "Therefore, the suppression of ASGR1 could potentially intercept its interaction with SARS-CoV, substantially diminishing the risk of viral infection." (PMID 40429734, 2025). "Furthermore, genetic depletion of several other factors, such as ASGR1, ASGR2, and ST6GAL1, also impaired viral infection, albeit with a 10–20% reduction." (PMID 39173055, 2024). "Then, we observed that similar to cells treated with siRNA targeting ASGR1, cells treated with monoclonal anti-ASGR1 also showed a decrease in the level of SARS-CoV-2 infection, noting that monoclonal antibodies are not as effective in inhibiting viral infection as siRNA." (PMID 38355848, 2024).
COVID-19 (4 papers, 2021 to 2024). A disease caused by infection with severe acute respiratory syndrome coronavirus 2. "Compared with ACE2, conclusive evidence from the analysis of patient-derived liver samples from COVID-19 autopsies shows that ASGR1, highly expressed in hepatocytes, is more likely to be the main receptor for SARS-CoV-2 entry." (PMID 38355848, 2024). "Considering the reports of multiple organ injuries in COVID-19 patients, it is suggested that ASGR1 may be a key receptor for SARS-CoV-2 in liver attacks." (PMID 38034398, 2023). "Furthermore, since ASGR1 is a receptor for SARS-CoV-2 invasion of liver, inhibition of ASGR1 may reduce the risk of liver injury in COVID-19 patients." (PMID 36690631, 2023). "However, the exact roles of ASGR1 in COVID-19 and acute hepatitis in children are still unclear." (PMID 38034398, 2023). "In addition, ASGR1 also served as the receptor or co-receptor for virus invasion of liver, such as SARS-CoV-2, which results in liver damage frequently observed in COVID-19 patients." (PMID 36690631, 2023).
lung carcinoma (4 papers, 2016 to 2023). "ASGR1 showed higher differential expression in DM patients compared to CVD and lung cancer (2nd column)." (PMID 38034398, 2023).
Obesity (4 papers, 2021 to 2025). Accumulation of substantial excess body fat. "In obesity, ASGR1-deficient mice show increased visceral adipose tissue (VAT) lipid accumulation but decreased plasma lipid levels, potentially due to ASGR1-mediated lipid redistribution." (PMID 40852369, 2025). "ASGR1 deficiency impacts energetic homeostasis during obesity leading to improved plasma lipid levels but increased VAT lipid accumulation and liver damage." (PMID 38281933, 2024). "In summary, despite its beneficial impact on plasma lipid levels, the ASGR1 deficiency results in markers of altered energetic homeostasis during HFD induced obesity, being reflected by increased lipid accumulation in VAT and liver damage." (PMID 38281933, 2024). "Moreover, our group and others showed that ASGR1 deficiency promotes liver damage in mice and humans with obesity." (PMID 39616371, 2024). "Therefore, here we investigated the contribution of ASGR1 in the development of metabolic syndrome and obesity." (PMID 38281933, 2024). "The molecular mechanisms by which ASGR1 could affect the onset of metabolic syndrome and obesity are unclear." (PMID 38281933, 2024). "Under obesogenic conditions, such as high-fat diet feeding, it is unclear whether ASGR1 can potentially reprogram hepatocyte metabolism and have a favorable effect on lipid profiles, thereby impacting the onset of metabolic syndrome and obesity." (PMID 38281933, 2024). "The cholesterol-lowering effect upon ASGR1 deficiency could be attributed to several factors such as reduction of intestinal absorption, de novo hepatic cholesterol synthesis, VLDL secretion, or increase of clearance by tissue uptake, as well as obesity." (PMID 34762653, 2021).
colorectal cancer (3 papers, 2012 to 2016). A primary or metastatic malignant neoplasm that affects the colon or rectum. "The only report of association with cancer is the reported increase in the rate of cell division of colorectal carcinoma cell lines when grown on ASGR1 coated surfaces, which makes both ASGRs intriguing hits." (PMID 23251904, 2012).
diabetes (3 papers, 2023 to 2025). "Genetically mimicked ASGR1 inhibitors had little association with cholelithiasis, adiposity or diabetes, despite an inverse association with HbA1c." (PMID 37400795, 2023). "On the other hand, asialoglycoprotein receptor 1 (ASGR1), Niemann–Pick disease, type C1 (NPC1), and AXL, as well as co-receptors of ACE2, such as heparan sulphate and scavenger receptor, class B type 1 (SR-B1), are downregulated in diabetes." (PMID 39273582, 2024).
Insulin resistance (3 papers, 2024 to 2025). Increased resistance towards insulin, that is, diminished effectiveness of insulin in reducing blood glucose levels. "It has been reported that the deficiency of ASGR1 may alleviate diet‐induced systemic insulin resistance via improved hepatic insulin sensitivity." (PMID 39949133, 2025). "Remarkably, ASGR1−/− mice did not present steatosis nor insulin resistance compared to WT mice, suggesting that the intracellular fat already present in the liver is oxidized rather than accumulated as intracellular fat to induce steatosis." (PMID 38281933, 2024).
liver cirrhosis (3 papers, 2022 to 2025). "In addition, based on liquid biopsy technology, recent studies have analyzed the phenotypic and genetic markers of ASGR1 expression in circulating epithelial cells (CECs) from the peripheral blood of patients with liver cirrhosis (LC) and HCC." (PMID 40852369, 2025). "Given that GP73 is a candidate target of ASGR1 and is highly expressed in patients with liver cirrhosis or HCC39, we first examined their relationship in these patients and observed negative correlations between elevated circulating GP73 levels and reduced ASGR1 mRNA expression." (PMID 38459023, 2024). "Interestingly, there was a significant difference between ASGR1 expression when analyzing liver cirrhosis and cancer occurrence together (p = 0.033)." (PMID 36518850, 2022). "We also found that decreased hepatic ASGR1 expression correlates with increased serum levels of GP73, hepatic ER stress, and biomarkers of liver injury in patients with liver cirrhosis." (PMID 38459023, 2024). "We found an inverse correlation between hepatic ASGR1 mRNA expression and serum levels of liver function biomarkers, including alanine aminotransferase (ALT), aspartate aminotransferase (AST), alkaline phosphatase (ALP) and gamma-glutamyl transferase (GGT), in patients with liver cirrhosis." (PMID 38459023, 2024).
Thrombocytopenia (3 papers, 2022 to 2025). A reduction in the number of circulating thrombocytes. "Conversely, activators could address thrombocytopenia by modulating the ASGR1-Notch1-thrombopoietin axis." (PMID 40429734, 2025).
essential hypertension (2 papers, 2023 to 2026). Hypertension that presents without an identifiable cause. "This study showed that the single nucleotide polymorphism rs34870220 of ASGR1 was associated with the occurrence of essential hypertension." (PMID 37667265, 2023). "Plasma ASGR1 levels were significantly higher in hypertensive patients with CAD than in those with hypertension alone (p < 0.001) and higher ASGR1 expression is accompanied by more severe coronary lesions and adverse clinical phenotypes." (PMID 42048115, 2026). "Through a PubMed literature search, only one study on ASGR1 and hypertension was obtained." (PMID 37667265, 2023).
fatty liver disease (2 papers, 2019 to 2023). A reversible condition wherein large vacuoles of triglyceride fat accumulate in liver cells via the process of steatosis. "ASGR1 inhibitors promote cholesterol excretion by upregulating liver X receptor α, which may cause hepatic steatosis and elevate liver enzymes." (PMID 37400795, 2023).
heart attack (2 papers, 2017 to 2022). "Recently, a rare variant in ASGR1 gene was found to lower the risk of a heart attack by more than one-third in Icelanders." (PMID 28449691, 2017).
liver dysfunction (2 papers, 2019 to 2022). "Furthermore, we found that the percentage of CECs without ASGR1 expression increased upon liver dysfunction (Child Pugh-Turcotte stage), although this increase was not significant (p = 0.74)." (PMID 36518850, 2022).
type 2 diabetes (2 papers, 2023). "Within CKB, TFPI, PGF, F2R, and ASGR1 were each significantly associated with all 4 CVD risk factors (smoking, SBP, adiposity, and type 2 diabetes)." (PMID 37940228, 2023). "Moreover, FURIN, ASGR1, SORT1, TFPI, PGF, F2R, and EFNA1 were also associated with SBP, adiposity, and type 2 diabetes." (PMID 37940228, 2023). "We conducted a drug-target Mendelian randomization study to assess genetically mimicked effects of ASGR1 inhibitors on all-cause mortality and 25 a priori outcomes relevant to lipid traits, CAD, and possible adverse effects, i.e. liver function, cholelithiasis, adiposity and type 2 diabetes." (PMID 37400795, 2023).
Acute hepatitis (1 paper, 2023). Acute hepatic injury resulting from inflammation typically accompanied by increased serum alanine transaminase activity. "The low level of ASGR1 in children may be related to immune dysfunction caused by adenovirus infection, which could explain the occurrence of acute hepatitis." (PMID 38034398, 2023).
alcoholic fatty liver disease (1 paper, 2024). Lipid infiltration of the hepatic parenchymal cells that is due to alcohol abuse. "Therefore, we first detected the expression of ASGR1 and ACE2 on the constructed non-alcoholic fatty liver disease cell model." (PMID 38355848, 2024). "It was found that compared with normal THLE-2 cells, the mRNA level of ACE2 was significantly increased in THLE-2 cells of the non-alcoholic fatty liver disease cell model, but ASGR1 was not significantly changed." (PMID 38355848, 2024).
cholelithiasis (1 paper, 2023). The presence of crystallized deposits forming in the gallbladder or biliary tree, primarily composed of cholesterol, bilirubin, and bile. "ASGR1 inhibitors may increase the risk of cholelithiasis through elevating biliary cholesterol excretion, similar to adenosine triphosphate-binding cassette transporters G5/8 (ABCG5/8)." (PMID 37400795, 2023).
delirium (1 paper, 2023). A disorder characterized by confusion; inattentiveness; disorientation; illusions; hallucinations; agitation; and in some instances autonomic nervous system overactivity. "Only four proteins were associated with delirium in both age groups: IL-8, IL-6, leukemia inhibitory factor (LIF), and asialoglycoprotein receptor 1 (ASGR1)." (PMID 37156856, 2023). "A few proteins (IL-8, LTBR, TNF-R2 postoperatively; IL-8, IL-6, LIF, ASGR1 by pre- to postoperative change) and 12 networks were common to delirium in both age groups." (PMID 37156856, 2023).
depression (1 paper, 2024). "In the search of an explanatory model for the observed associations between depression and the blood levels of PPP3R1, CD63, and ASGR1, platelets emerge as potentially pivotal players." (PMID 38812487, 2024). "Other interesting findings involve two proteins, ASGR1 and CD63, corresponding to genes that may offer new insights into the pathophysiological processes of depression." (PMID 38812487, 2024).
dermatitis (1 paper, 2022). An inflammatory process affecting the skin. "In an animal model, it was suggested that the C-type lectin receptor Clec10a in mice and the similar Asgr1 protein in humans, regulate the inflammation associated with mite-induced dermatitis." (PMID 35334542, 2022).
dry eye (1 paper, 2009). "One lacrimal gland gene upregulated by 17β-estradiol and downregulated by testosterone is asialoglycoprotein receptor 1, which has been linked to the development of exocrine gland inflammation and dry eye." (PMID 19693291, 2009).
epidermoid carcinoma (1 paper, 2020). "The ASGR1-dependence of the αASGR1-RSPO mimetics was also confirmed in another ASGR1 negative cell line, A431, which is derived from a human epidermoid carcinoma and expresses ASGR genes at very low levels." (PMID 32811902, 2020).
fetal growth restriction (1 paper, 2021). A fetus that does not grow beyond the 10th percentile of conventionally accepted weight for gestational age. "RNA sequencing to compare normal pregnancy with fetal growth restriction (FGR) pinpointed RP11-552M6.1, LINC01291, and ASGR1 (umbilical cord blood) and SFRP2, miR-432-5p, and miR-1306-3p (maternal peripheral blood)." (PMID 34880903, 2021).
hepatoblastoma (1 paper, 2012). Hepatoblastoma (HB) is a malignant hepatic tumor and is the most common pediatric liver cancer. "Hepatoblastoma overexpresses ASGR1 asialoglycoprotein receptor 1, and ASGR2." (PMID 23251904, 2012).
Hyperglycemia (1 paper, 2024). An increased concentration of glucose in the blood. "Therefore, exploring whether ASGR1 regulates GP73 in the context of SARS-CoV-2-induced hyperglycemia merits further investigation." (PMID 38459023, 2024).
metastatic tumors (1 paper, 2022). "Metastatic tumors of HCC can also be targeted by GalNac‐siHK2 due to the expression of ASGR1 in HCC metastatic tumors." (PMID 35603967, 2022).
non-alcoholic fatty liver disease (1 paper, 2024). "The result suggests that in non-alcoholic fatty liver disease, SARS-CoV-2 can infect hepatocytes through ASGR1 and ACE2." (PMID 38355848, 2024).
sarcopenia (1 paper, 2025). Progressive decline in muscle mass due to aging which results in decreased functional capacity of muscles. "Our MR analysis found that ASGR1 was positively correlated with the sarcopenia‐related traits." (PMID 39949133, 2025). "Among them, the significant associations of CTSB (negative association) and ASGR1 (positive association) with sarcopenia‐related traits were observed to have consistent directional associations in both MR‐based studies and observational studies." (PMID 39949133, 2025).
Sepsis (1 paper, 2024). Sepsis is defined as life-threatening organ dysfunction caused by a dysregulated host response to infection. "Contrarily, ASGR1 deficiency has also been reported to attenuate liver injury in LPS-induced sepsis mice." (PMID 38459023, 2024).
steatosis (1 paper, 2024). Increased lipid within the cytoplasm of cells. "However, ASGR1 deficient mice, in the same study showed additional metabolic changes related to increased activation of AMP-activated protein kinase (AMPK), which plays a role in suppressing hepatic fatty acid synthesis by inhibiting SREBP-1c, thus preventing the adverse effects of steatosis." (PMID 38281933, 2024).
Streptococcus pneumoniae infection (1 paper, 2021). "More importantly, in line with our findings, Asgr1-deficient mice showed more severe liver injury and elevated hepatocyte death upon Streptococcus pneumoniae infection than did WT controls, supporting genetic susceptibility to liver injury in ASGR1 deficiency." (PMID 34762653, 2021).